NOTCH1 (notch receptor 1)
Diseases named in the same sentence as NOTCH1 in open-access papers (continued):
Sharing a sentence is not in itself a finding about the gene and the disease.
breast cancer (continued). "The most striking research in our study was the evaluation of correlation between SIRT1 protein and Notch1 signaling with breast cancer prognosis." (PMID 25420528, 2014). "We further investigate the N1IC expression of Notch1 signaling and the downstream transcription factor, Snail, with regard to prognosis in breast cancer." (PMID 25420528, 2014). "Recently, miR-146a was also found to interact with Notch via regulation of Numb in breast carcinomas and to stimulate NF-κB activity through Notch 1 [reviewed in Ref." (PMID 25717438, 2014). "The prognostic impact of SIRT1 expression and Notch1 signaling was also analyzed in 122 of all 150 patients with breast carcinoma (because of the missing survival data in 28 patients)." (PMID 25420528, 2014). "Canonical Notch pathway activity in reporter assays was repressed in UC cell lines compared to normal cells and a mammary carcinoma cell line, but was induced by transfected NOTCH1." (PMID 25167871, 2014). "Staining of a tissue microarray containing 78 triple negative breast cancers for NICD1 identified 3 tumors (3.8%) with strong diffuse nuclear staining, a pattern similar to that in xenografted breast cancer cell lines with activating deletions of NOTCH1." (PMID 23825651, 2013). "Hyperactivated Notch1 signaling was first implicated in mammary tumorigenesis in studies of the MMTV model, which showed that N1ICD expression in MMTV-Neu mammary tumors is due to an MMTV insertion in the Notch1 locus." (PMID 23826634, 2013). "The inhibition of STAT3 by LLL12 also down-regulated the expression of several known STAT3-regulated genes in breast cancer stem-like cells such as Cyclin D1, survivin, Bcl-2, Bcl-XL and an IL-6 regulated gene, Notch1." (PMID 24376586, 2013). "Our findings in these mammary tumor models point to NOTCH1 as a potential therapeutic target in breast cancer onset and progression." (PMID 23826634, 2013). "NOTCH1 and NOTCH4 pro-viral integration sites mediate mammary tumour formation, Notch4 is upregulated in T-ISC in primary non-invasive and invasive ER positive breast cancers and Notch1 overexpression in breast cancer correlates with worse prognosis." (PMID 23982961, 2013). "High expression of NOTCH1 was observed in human breast cancer and colorectal cancer, both of which are correlated with poor outcome of cancer patients." (PMID 22539939, 2012). "Several studies also suggested that Notch-1 signaling pathway is involved in drug resistance in a variety of human cancers including breast cancer." (PMID 22949821, 2012). "This analysis revealed that the mammary tumor-initiating cell in this mammary tumor model is relatively rare and that the bulk of the NOTCH1-transformed mammary tumor cells lack the capacity to initiate disease in immunodeficient recipient mice." (PMID 22992387, 2012). "Immunohistochemical analysis of tumor sections with antibodies against Cytokeratins K8/18, K5, and K14 revealed that the NOTCH1-induced mammary tumors consist of K8/18-expressing cells, confirming that the tumor consists of primarily luminal epithelial cells." (PMID 22992387, 2012). "Four independent NOTCH1-driven mouse mammary tumors were injected as serial dilutions into the thoracic mammary fat pad of immunodeficient mice, and recipient mice were monitored for disease development." (PMID 22992387, 2012). "The expression of Notch-1 in As2O3-treated breast cancer cells was assessed by RT-PCR and Western blotting analysis, respectively." (PMID 22949821, 2012). "Changes in Notch4 are of particular interest because previous studies have shown that blocking NOTCH4 receptor activity inhibits tumor formation of xenografted breast cancer cells, whereas blocking NOTCH1 has less of an effect." (PMID 22225988, 2012). "Mammary tumor-bearing mice were treated with doxycycline to suppress NOTCH1 expression, and disease recurrence was monitored." (PMID 22992387, 2012).
breast cancer (continued). "High NOTCH1-receptor levels have been linked with basal-like, triple-negative (estrogen receptor-, progesterone receptor-, and HER2-negative) breast cancer, and NOTCH1 levels correlate with abbreviated survival." (PMID 22992387, 2012). "In vivo limiting-dilution analysis reveals that only a small percentage (~1/3,000) of NOTCH1-driven mammary tumor cells are capable of transplanting disease, revealing that mammary tumor-initiating cells contribute to disease pathogenesis in this model." (PMID 22992387, 2012). "We found that both Notch-1 mRNA and protein levels were down-regulated after As2O3 treatment in all three breast cancer cell lines." (PMID 22949821, 2012). "To determine the specific effects of NOTCH1 activation/inhibition on bulk mammary tumor growth and on mammary tumor-initiating cells, we generated a mouse mammary tumor model in which human intracellular NOTCH1 expression is doxycycline regulated." (PMID 22992387, 2012). "We were, however, unable to detect Nanog expression in primary NOTCH1-transformed mammary tumors by using immunohistochemistry or quantitative real-time PCR (not shown)." (PMID 22992387, 2012). "We validated this finding in multiple NOTCH1-transformed mammary tumor cell lines using quantitative real-time PCR and observed on average a fivefold decrease in Nanog mRNA levels in doxycycline-treated mammary tumor cells." (PMID 22992387, 2012). "We demonstrate that NOTCH1-transformed mouse mammary tumors harbor a rare mammary tumor-initiating population and that NOTCH1 contributes to mammary tumor-initiating activity." (PMID 22992387, 2012). "Consistent with one study that As2O3 inhibited Notch-1 and its target gene Hes-1 in gliomas, we found that As2O3 down-regulated the expression of Notch-1 and its target genes in breast cancer cell lines." (PMID 22949821, 2012). "Using an in vivo limiting-dilution assay, we provide evidence that NOTCH1-transformed mammary tumors are functionally heterogeneous and estimate the frequency of mammary tumor-initiating cells to be approximately 1/3000 cells." (PMID 22992387, 2012). "The tumorsphere assays revealed that NOTCH1 is required both for the initiation and maintenance of tumorspheres in vitro and potentially for mammary tumor-initiating activity in vivo." (PMID 22992387, 2012). "With this dox-regulated NOTCH1 mammary tumor model, we demonstrate that NOTCH1 inhibition results in mammary tumor regression in vivo and prevents disease recurrence in four of six tumors tested." (PMID 22992387, 2012). "To determine the consequences of NOTCH1 inhibition on mammary tumor growth/survival, we treated the mammary tumor cell lines with doxycycline for 72 hours and performed an MTT analysis." (PMID 22992387, 2012). "Human breast cancer cells were transfected with Notch-1 siRNA and cDNA, respectively, using Lipofectamine 2000." (PMID 22949821, 2012). "Our findings in this NOTCH1 mammary tumor model implicate NOTCH1 as a potential therapeutic target in breast tumor-initiating cells." (PMID 22992387, 2012). "GASC1 demethylase activity has been shown to regulate the expression of genes critical for stem cell self-renewal, including NOTCH1 and NANOG, and possibly to be linked to the stem cell phenotypes in breast cancer." (PMID 23148692, 2012). "Consistent with the in vivo limiting-dilution analyses, a subpopulation of NOTCH1 transformed mammary tumor cells grow in an in vitro tumorsphere assay and importantly, doxycycline treatment significantly reduces sphere number and size." (PMID 22992387, 2012). "We also demonstrated that NOTCH1 signaling is required for mammary tumor-initiating cell activity, as NOTCH1 inhibition results in rapid mammary tumor regression and delays and, in some cases, prevents disease recurrence." (PMID 22992387, 2012). "Nanog expression was detected in the nuclei of NOTCH1-transformed mammary tumor cell lines and in primary tumorspheres." (PMID 22992387, 2012).
breast cancer (continued). "Primary NOTCH1-transformed mammary tumor cells formed spheres in culture at a rate of 1 in 268 (0.37%)." (PMID 22992387, 2012). "Together, these data suggest that NOTCH1 contributes to mammary tumor-initiating activity in vitro and potentially in vivo." (PMID 22992387, 2012). "To address the role of NOTCH1 in mammary gland development, transformation, and mammary tumor-initiating cell activity, we developed a doxycycline-regulated mouse model of NOTCH1-mediated mammary transformation." (PMID 22992387, 2012). "More recently, silencing of Lunatic Fringe, the glycosylase that regulates NOTCH1 ligand activity, has been observed in patients with basal-like breast cancer, and increased levels of intracellular NOTCH1 are detected in these patients' cells." (PMID 22992387, 2012). "Previous investigations have determined that overexpression of Notch-1 and Notch-4 plays a critical role in breast tumorigenesis and that PEA3 overexpression is associated with aggressive breast cancers, particularly the triple-negative subtype." (PMID 21679465, 2011). "Increased coexpression of Notch-1 and its ligand Jagged-1 predicts the poorest overall survival in women with breast cancer." (PMID 21847123, 2011). "Overexpression of constitutive, active forms of Notch-1 (N1IC) or Notch-4 (N4IC) form spontaneous murine mammary tumors in vivo." (PMID 21679465, 2011). "Expression of Notch1 and its ligand, JAG1, is associated with the poorest breast cancer survival and increased levels of VEGFR-2." (PMID 21731759, 2011). "Overexpression of constitutively active forms of Notch-1, Notch-3, and Notch-4 develop spontaneous murine mammary tumours in vivo." (PMID 21847123, 2011). "Real-time PCR and Western blot analysis were performed to detect Notch-1, Notch-2, Notch-3 and Notch-4 receptor expression in breast cancer cells when PEA3 was knocked down by siRNA." (PMID 21679465, 2011). "Herein we have provided evidence of a novel therapeutic strategy to be exploited for the treatment of triple-negative breast cancer and potentially other breast cancer subtypes where PEA3 regulates Notch-1 and Notch-4." (PMID 21679465, 2011). "Taken together, PEA3 is required for Notch-1 transcription in at least three subtypes of breast cancer cells: MDA-MB-231, SKBr3 and MCF-7." (PMID 21679465, 2011). "Notch-1 and Notch-4 are potent breast oncogenes that are overexpressed in triple-negative and other subtypes of breast cancer." (PMID 21679465, 2011). "Together these data suggest that the therapeutic potential of NRR antibodies is higher in tumors that have intact extracellular Notch1 and depend on ligand for Notch1 activation; breast cancer is one such tumor." (PMID 20161710, 2010). "In breast cancers, it was found that BCSCs preferentially expressed some "stemness" genes, including Notch1 and β-catenin." (PMID 20569497, 2010). "Recently, ErbB2 was shown to induce Notch1 activity in breast cancer cells, which is consistent with its ability to drive mammary stem cell proliferation, tumorigenesis and invasion." (PMID 20727204, 2010). "Hes1 is a target of Notch1 signaling, which is aberrantly activated in a variety of human cancers, including prostate, lung, colorectal, osteogenic, and breast carcinomas." (PMID 21106062, 2010). "In primary breast cancer-derived mammospheres, we detected intense nuclear staining for both cleaved Notch1 as well pErk1/2." (PMID 20030805, 2009). "Accumulation of the intracellular domain of Notch1 has been detected in a variety of breast cancers." (PMID 20030805, 2009). "Breast cancer cells in which the Notch pathway has been targeted, either by an inhibitor of γ-secretase or by Notch-1 RNAi, downregulate cyclin B1 and suffer G2/M arrest." (PMID 19513078, 2009). "For example, integrin-linked kinase (ILK), which is either activated or overexpressed in many types of cancers including breast cancer, can remarkably reduce the protein stability of Notch1 and thus decrease its half-life drastically." (PMID 19468305, 2009).
breast cancer (continued). "As many as 75% of breast cancers showed accumulation of cleaved Notch1 (27/35) and expression of Hes1/5 (27/36)." (PMID 20030805, 2009). "We detected the presence of active, cleaved Notch1, along with downstream targets of the Notch pathway, Hes1/Hes5, in ~75% of breast cancers, clearly indicating that in a large proportion of breast cancers Notch signaling is aberrantly activated." (PMID 20030805, 2009). "We report here that there is a general increase in the expression levels of Notch 1, 2, 4, Jagged1, Jagged2, and Delta-like 4 proteins in breast cancers, with simultaneous upregulation of multiple Notch receptors and ligands in a given cancer tissue." (PMID 20030805, 2009). "Transgenic mice overexpressing active Notch1, Notch3, or Notch4 homologs all developed mammary carcinoma." (PMID 19660128, 2009). "We analyzed protein expression of the Notch-1 intracellular domain and survivin by immunohistochemistry in a series of basal breast cancer patients." (PMID 19025652, 2008). "In the present study, we have shown that Notch-1 is preferentially expressed in breast cancer, as compared with normal tissues, segregates with basal disease, and correlates with abbreviated survival." (PMID 19025652, 2008). "Targeting Notch-1 signaling in model breast cancer cells lowered survivin levels, resulting in pronounced anti-tumor effects." (PMID 19025652, 2008). "The developmental signaling regulator Notch-1 was highly expressed in breast cancer, compared with normal tissue, and was segregated with basal disease." (PMID 19025652, 2008). "Activated Notch-1 was abundantly expressed in all cases examined of basal breast cancer, and was localized to both the cytosol and nuclei of tumor cells." (PMID 19025652, 2008). "Analysis of Pearson's correlation coefficient indicated that Notch-1 and survivin co-segregated in basal breast cancer." (PMID 19025652, 2008). "The Pearson's correlation coefficients between Notch-1 and survivin were 0.1804 and -0.0674 for ER-negative and ER-positive breast cancers, respectively (P < 0.0001)." (PMID 19025652, 2008). "Pooled estimates of Pearson's correlation coefficient between Notch-1/keratin-5 were 0.3315 and 0.2043 for ER-negative and ER-positive breast cancers, respectively (P = 0.04)." (PMID 19025652, 2008). "Supervised hierarchical clustering of 232 cases of human breast cancer, using intrinsic gene analysis, revealed that higher expression of Notch-1 segregated with basal breast cancer." (PMID 19025652, 2008). "For example, the constitutively activated form of Notch acts as a bona fide oncogene in leukaemia and in murine breast cancer, while recent data show that Notch-1 can function as a tumour suppressor gene in skin cancer." (PMID 15685243, 2005). "NOTCH1 is important in breast cancer because it aids cancer cell growth and survival." (PMID 41561443, 2026). "In breast cancer and colorectal cancer cells, lycopene significantly downregulates the expression of Notch1 and its ligand Jagged1, blocks nuclear translocation of the NICD, and subsequently suppresses Hes1 expression, leading to inhibition of cell proliferation and induction of apoptosis." (PMID 41602823, 2026). "This lack of subtype-specific mechanistic insights may lead to inconsistent efficacy-for example, resveratrol inhibits Notch1 (a key pro-tumor factor in breast cancer) to suppress breast cancer growth, underscoring the need for subtype-specific research." (PMID 41602823, 2026). "To test whether PTPN23, HCN2, or SGK3 affect Notch levels in breast cancer cells, we first evaluated by Western blot the levels of NOTCH1-3 in a panel of five breast cancer lines of different origin." (PMID 39663000, 2025). "In tumors such as breast cancer, various members of the Notch pathway, including Notch1, Notch3, DLL1, and DLL3, have been implicated in either promoting or inhibiting angiogenesis." (PMID 40486870, 2025).
breast cancer (continued). "Nearly 20 years ago, Reedijk and colleagues analysed a cohort of patients with early breast cancer (n = 184) and detected by univariate analysis a worse ten-year OS probability of 49% in patients with high NOTCH1 protein expression, compared to 64% with low NOTCH1 protein expression (via IHC)." (PMID 39153127, 2025). "In basal-like breast cancer, we found that a low WWOX/HIF1A ratio is associated with particularly aggressive disease because it promotes EMT via ZEB1 and ADAM9, facilitates ECM remodelling via MMP2 and ITGA1, and enables immune evasion via NOTCH1 and TLR4." (PMID 41007296, 2025). "NOTCH1 mRNA has been supposed to be involved in resistance to chemotherapy before by various mechanisms, including epithelial-mesenchymal transition, self-renewal of breast cancer stem cells and activation of proliferation pathways." (PMID 39153127, 2025). "Furthermore, YAP with TEADs enhances Jagged1-Notch1 signaling; Notch1 promotes YAP stability through inhibited β-TrCP-mediated degradation and formation of a YAP1- jagged-1/Notch1-positive feedback loop in breast cancer cells." (PMID 39752217, 2025). "Notch activates the PI3K/AKT/mTOR pathway to promote tumor growth.Notch1 activates the mTORC1 pathway.The mTOR pathway cooperates with Notch signaling and metabolic reprogramming to maintain breast cancer stem cell characteristics and promote therapy resistance." (PMID 41050674, 2025). "Some studies have indicated that tumor-secreted CCL20 activates granulocyte–monocyte progenitor cell differentiation through its receptor CCR6, leading to the expansion of PMN-MDSCs, which activates the CXCR2/NOTCH1/HEY1 signaling pathway to increase ALDH+ breast cancer tumor stem cells." (PMID 40722739, 2025). "Furthermore, this research showed that inhibiting Notch‐1 led to the suppression of growth in breast cancer cells by inducing apoptosis, underscoring the oncogenic role of Notch signalling in cancer cells." (PMID 40100070, 2025). "Notch1 has been shown to activate ChK1 through ATR in breast cancer, thus it is possible that its inhibition may result in reduced activation in melanoma cells." (PMID 40437523, 2025). "Besides, overexpression of circ_000911 has suppressed breast cancer xenografts by restoring the miR‐449a/Notch 1 axis." (PMID 40761890, 2025). "Notch 1 plays a crucial role in breast cancer by promoting cell proliferation and survival." (PMID 37726449, 2024). "Leptin also increases the activity of the JAG1 receptor NOTCH1 in breast cancer cells." (PMID 39408921, 2024). "Studies have also shown that kaempferol can inhibit the proliferation and induce apoptosis of breast cancer SK-BR-3 cells in vitro, which may be related to the regulation of Notch1 and Cleaved caspase-3 protein expression." (PMID 39221164, 2024). "It would be interesting to know whether the TGF-β activation in metastatic breast cancer cells leads to Notch 1 upregulation." (PMID 39430758, 2024). "Based on our finding that NOTCH1 transcriptionally activates USP11 expression, it might be interesting to study the USP11-NOTCH1 positive feedback loop in other cancer types, including colorectal and breast cancer." (PMID 38007584, 2024). "Breast cancer cells showed cytoplasmic immunostaining for Jagged-1, Notch-1, Notch-2, and HERP-1." (PMID 38314334, 2024). "Paeonol also inhibited breast cancer cell invasion by suppressing the signaling pathway of the gene encoding the Notch-1 one-way transmembrane receptor and reduced the expression level of transgelin two in MCF-7/PTX cells, thereby reversing the resistance of breast cancer cells to paclitaxel." (PMID 39588155, 2024). "The ectopic expression of miRNA-34a in metastatic breast cancer cell-line BT-549 significantly inhibited cell migration and invasion by directly targeting epithelial to mesenchymal transition (EMT)-associated protein NOTCH1." (PMID 38057687, 2024).